CDKN2A (cyclin dependent kinase inhibitor 2A)
Diseases named in the same sentence as CDKN2A in open-access papers (continued):
Sharing a sentence is not in itself a finding about the gene and the disease.
tumor (continued). "This addition to the grading criteria is based on the results of several studies showing that CDKN2A/B homozygous deletion results in patient outcomes similar to grade 4 tumours, even in the absence of high grade histological features." (PMID 37239289, 2023). "The tumor showed EGFR C797S, T790M, exon 19 deletion (T751_I759>N), CDK4 amplification, MDM2 amplification, CDKN2A/B loss, MTAP loss, low MSI, low TMB and negative PD-L1." (PMID 38111812, 2023). "They presented classical features (pleomorphic tumor cells, spindle cells, xanthomatous cells, eosinophilic granular bodies with reticulin staining surrounding individual cells, and CD34 immunopositivity), and a homozygous deletion of CDKN2A." (PMID 37349135, 2023). "While these studies serve as an indicator that the presence of a CDKN2A/B HD changes tumour response to treatment, given that they did not look at IDH-mutant tumours, it is hard to put them into the context of the current classification." (PMID 37504251, 2023). "Both of the two assays showed that knock-down of CDKN2A could results an enhanced proliferative ability in SW1088 cells, which showed the CDKN2A also act as a tumor suppressor in LGG cells." (PMID 36961395, 2023). "It was not a surprise that the assessment of CDKN2A CpG island methylation in our study exhibited hypermethylation in tumor tissue in comparison to the normal control in all of the analyzed human tumors with statistically significant results." (PMID 37626750, 2023). "The results revealed that LIAS, DLAT, PDHA1, and CDKN2A were significantly upregulated in LUAD tumors compared to normal tissues, while ATP7B, SLC31A1, FDX1, MTF1, and GLS were significantly downregulated in tumor tissues." (PMID 36983664, 2023). "Concomitant CDKN2A deletion did not appear as a predictive molecular marker of tumor resistance or unresponsiveness." (PMID 36831610, 2023). "Deep deletions of chromosome regions containing FBXW7, CDKN2A, CDKN2B, and MTAP could be identified in the MPM693 patient-derived cell line and the corresponding tumor." (PMID 37345150, 2023). "Patient selection by high mRNA expression of CDK4, while CDKN2A was not overexpressed at baseline tumor followed an extensive investigation." (PMID 37875500, 2023). "CDKN2A was found to be upregulated in cancerous tissues versus normal ones and that predicted the progression of tumor stage, grade, and metastasis in addition to poor prognosis under different forms of tumors." (PMID 37626750, 2023). "The transient silencing of ANRIL/CDKN2B-AS1 triggered an increase in INK4A/CDKN2A and INK4B/CDKN2B expression and impaired the metastatic ability of CM and UM cells in vitro; also, tumor formation induced by UM cells was inhibited both in vitro and in vivo by lncRNA knockdown." (PMID 36765733, 2023).
tumor (continued). "After collecting and processing the data in TCGA-KIRC database, the researchers compared the content of MYCN and other factors in normal kidney tissue and pathological tissue and found CDKN2A and ZBP1 in tumor tissues were up-regulated and MYCN was down-regulated." (PMID 37878133, 2023). "In TG18, amplification was already present in the primary grade 3 tumor and was not coupled with CDKN2A deletion; in the others, amplification was acquired upon progression, concomitantly with CDKN2A deletion." (PMID 37932833, 2023). "In summary, these findings suggest that the upregulation of Cdkn2a in GTML as compared to GMYC might reflect a clinically relevant feature also present and affecting tumor prognosis between MYC-high and MYCN-high human Group 3/4 MBs." (PMID 36869047, 2023). "To characterize senescence status of tumor cells, we re-clustered ductal 2 cells and annotated all ductal 2 cells as CDKN2A+ and CDKN2A-, or senescent versus non-senescent tumor cells." (PMID 37398643, 2023). "In the pattern defined as focal expression, there was no CDKN2A homozygous deletion (0/89) if more than 5% of tumor cells were expressing p16." (PMID 36900302, 2023). "Notably, we found CDKN2A/B HD in the xenograft model (YMG25R-PDX), which was only derived from the recurrent tumor." (PMID 38012788, 2023). "This mutation-specific vaccine elicited robust peripheral T cell responses and intratumoral inflammatory reactions, irrespective of any known tumor-intrinsic molecular markers, including CDKN2A/B homozygous deletion and methylation status." (PMID 35203456, 2022). "In mice with mutant Kras and deletion of Cdkn2a in lung epithelial cells, lung tumors develop with activation of ERK, RHOA, and FAK, and subsequent deletion or pharmacologic inhibition of FAK resulted in tumor regression." (PMID 35763345, 2022). "Specifically, there was a downward trend of FDX1 and LIAS expression and an upward trend of CDKN2A expression regardless of tumor stage or histological grade." (PMID 35627236, 2022). "We found that CDKN2A and CMTM8 were tumor promoters, while ILK was tumor inhibitors." (PMID 35429970, 2022). "At the protein level, it was found that CDKN2A was highly expressed in the HCC tumor tissues as compared to the non-tumor tissues using two-color immunofluorescence." (PMID 36428805, 2022). "Moreover, the expression of CDKN2A (p = 3.5e−10) and GLS (p = 5.2e−17) in UCEC patients with low tumor grade were higher than in those with high tumor grade." (PMID 35937995, 2022). "Along with CDKN2A, other INK4 family members, CDKN2B, CDKN2C, and CDKN2D, also showed a good ability to distinguish tumor from normal tissue, particularly CDKN2C, suggesting that they can be used as biomarkers for the screening, diagnosis, and prognosis prediction of HCC." (PMID 35771229, 2022). "Moreover, the result of Western blots showed that the expressions of SDHB and CCS were downregulated and that of ULK1, CDKN2A, and CMC1 were upregulated in tumor tissues compared with normal tissues." (PMID 36505872, 2022). "This suggests ADM_Normal is a transition state more similar to normal ductal cells and largely lacking genomic alterations, while ADM_Tumor is more related to PanIN and has a few alterations (for example, CDKN2A, aneuploidy)." (PMID 35995947, 2022). "CDKN2A and PTEN are tumour suppressors with the highest number of deletions." (PMID 35975235, 2022).
tumor (continued). "Additionally, increased mRNA level of CDKN2A, DLAT, GLS, LIPT1, and MTF1 in tumor were observed compared to normal group." (PMID 36703728, 2022). "ReactomeFIViz enrichment analysis in Cytoscape showed an association of seven (EDNRB, CDKN2A, VEGFD, FOS, GNG11, TGFBR2, and BIRC5) of the forty-four nodes of the LC-BC CCPs with signaling pathways related with the acquisition of tumor characteristics." (PMID 36101460, 2022). "Conversely, expression of XCL1, which when produced by tumor cells may induce PD1/PD‐L1 interaction and dysfunction of CD8+ T cells in the tumor microenvironment, was higher in CDKN2A/BHDIFN‐IHD tumors than in CDKN2A/BHDIFN‐IWT tumors." (PMID 35253368, 2022). "Among these DEGs, CDKN2A, GNG7, GSDMD, and POLG are known tumor suppressors in GC." (PMID 36230863, 2022). "MiRNA-31 encoded by the MIR31HG gene, positioned adjacent to CDKN2A/B at Chromosome 9, is compromised in >72% of GBM, and its reintroduction reduces tumor burden by inhibiting NF-κB signaling, independent of CDKN2A/B status." (PMID 36009578, 2022). "We also investigated the relationship between CDKN2A deletion and the presence or absence of TILs in the tumor microenvironment." (PMID 35739333, 2022). "By contrast, a deletion of CDKN2A/B on 9p in the relapsed bone marrow was identified in the primary bone marrow as a minor clone population, but not in the primary tumor specimen." (PMID 34553842, 2022). "Losses of PTEN and CDKN2A/CDKN2B 7, 20 were frequent events in 7 and 8 tumor foci, respectively." (PMID 34987659, 2022). "Fluorescence in situ hybridization (FISH) detection showed that tumor cells were intact on chromosomes 1p and 19q, CDKN2A nondeletion, and EGFR nonamplification." (PMID 35663322, 2022). "In our in vivo pharmacological program, the CD3 model harboring CDKN2A/2B showed a significant tumor growth inhibition (p = 0.02), while the CD7 model showed no tumor response (p = 0.85)." (PMID 36505864, 2022). "High frequency of genetic alterations of tumor suppressors (e.g., PTEN and CDKN2A/CDKN2B) and oncogenes (e.g., PDGFA and EGFR) suggested that these cancer driver genes might be responsible for initiation of mGBM but not contribute to the progression of mGBM." (PMID 34987659, 2022). "Hence, we conducted the first converge comprehensive landscape analysis of FAC-related gene CDKN2A in BRCA, including expression, prognostic values, DNA methylation, tumor microenvironment (TME) analysis, and drug sensitivity of CDKN2A in BRCA." (PMID 36052076, 2022). "We found that deregulated CDKN2A did not affect estimate, immune, and stromal score as well as tumor purity." (PMID 35832557, 2022). "Therefore, the cancer cells mainly expressed the known CSCC‐associated gene SERPINB3 (serpin family B member 3), tumor genes TP63, CDKN2A, and keratin gene KRT5 in squamous cells." (PMID 35986392, 2022). "The presence of CDKN2A/CDKN2B biallelic and monoallelic loss was tested employing FISH in 18 tumor samples with no discrepancies observed when compared to NGS." (PMID 35372034, 2022). "CTC CNAs, including amplifications of MYC, BCL6, DDR2, SOX2 and deletions of CDKN2A/B, were more likely to be shared with residual rather than primary tumor." (PMID 35087134, 2022). "The protein biomarkers assess hormone response (PR, FOXA1), aggressiveness (HER2), proliferation (Ki-67), cell cycle regulation (p16/CDKN2A) and stress response (COX2, SIAH2), while the clinicopathologic features include age, tumor size, margin status and palpability." (PMID 35567670, 2022).
tumor (continued). "This study effectively determined that BAP1, CDKN2A and NF2 alterations occur in pleural effusion-derived tumour cells at a higher frequency than what is typically seen in MM tumour samples, as well as identifying high frequency alterations for the TRAF7 and LATS2 genes." (PMID 34900693, 2021). "In tumor tissue, CDKN2A has a high expression level compared with normal tissue and reflects prognosis in tumor patients." (PMID 35004697, 2021). "Since the MOA agents listed for SOM meta-clades 21 through 24 have roles in DNA damage, defective CDKN2A, RPTOR and KRAS may contribute to chemosensitivity of tumor cell lines to these agents." (PMID 33909629, 2021). "To assess the prevalence of CDKN2A deletions in mUC, NSCLC, and RCC, we queried the Foundation Medicine clinical database, including 140,288 patient tumor samples, for the prevalence of patients with partial (one copy, CN1) or complete (zero copy, CN0) CDKN2A deletion." (PMID 34172722, 2021). "A single type of CDKN2A alteration (c.343G>T: p.Val115Leu) was detected in an AA sample, and a single type of HIC1 alteration (c.1571A>G: p.Lys524Arg) was confirmed in an AA tumor." (PMID 33778063, 2021). "Molecular examination of the tumor showed a truncating NF1 mutation, absence of BRAFV600 hotspot mutation and CDKN2A/B deletion." (PMID 33905054, 2021). "In the present study, we investigated the promoter methylation levels of MLH1, MGMT, CDKN2A, and RASSF1A in blood and tumor tissue DNA from 69 patients with TAMG, as well as in the healthy thymic epithelial tissue adjacent to the tumor available from 44 of them." (PMID 33192293, 2020). "The anatomical location of the tumour did not influence CDKN2A copy number status or p16 protein expression." (PMID 31916407, 2020). "Meanwhile, a deletion peak of CDKN2A and CDKN2B was also observed in these tumours." (PMID 33006444, 2020). "Multiple genes, such as CDKN2A, DAPK, MGMT, RARB, RASSF1A, and TERT, have been found to be methylated early in lung premalignant lesions, and the level of methylation increases with tumor progression from premalignant lesions to neoplasms." (PMID 32751497, 2020).
tumor (continued). "In the initial index patient’s tumor, WES analysis revealed amplification of chromosome 7 and deletion of chromosome 10 and focal deletion of CDKN2A locus on chromosome 9 along with an activating ectodomain EGFR A289V mutation, suggesting that the tumor cells had undergone chromothripsis." (PMID 31376079, 2020). "Since disruptions in Cdkn2a are commonly observed in clinical MPNST samples, we postulate that acceleration of tumor onset in BALB/c mice may be partially due to disruption of this locus." (PMID 32456131, 2020). "CDKN2A is one of the most frequently methylated genes across common cancer types and is often differentially silenced in primary tumors and tumor cell lines relative to non-malignant cells." (PMID 32314030, 2020). "Experiments in mice have shown that the Cdkn2b also exhibits a tumor suppressor role in MPM, as its deletion concomitant with Cdkn2a further accelerates MPM development (our unpublished results) offering a rationale for the predominant deletion of all three tumor suppressors in this locus in MPM." (PMID 32117751, 2020). "CDKN2A is the locus for two tumour suppressor genes—INK4A and P19-ARF." (PMID 31505839, 2019). "Due to intratumoral heterogeneity of tumor tissue and clonal enrichment of PDCs, some PDCs were not completely concordant with corresponding tumor tissue in detecting the CNVs of CDKN2A and CDKN2B." (PMID 31700061, 2019). "Furthermore, PRP induced the up-regulation of cyclin-dependent kinase inhibitors genes (CDKN2A; CDKN2, 2 and CDKN2C) which are considered important tumour suppressor genes." (PMID 31388092, 2019). "Three proteins and two clinical signatures were confirmed to be significantly related to the regrowth of NFPA, including cyclin-dependent kinase inhibitor 2A (CDKN2A/p16), WNT inhibitory factor 1 (WIF1), tumour growth factor beta (TGF-β), age and tumour volume." (PMID 31109334, 2019). "CDKN2A functions as inhibitors of CDK4 kinase, which denotes this gene as a tumor suppressor." (PMID 30871102, 2019). "Most importantly, the treatment demonstrated anti-tumor effect without de-repression of CDKN2A, raising the possibility of a p16-independent oncogenic pathway." (PMID 30101054, 2018). "We identified seven oncogenes (NRAS, EGFR, RXRA, HRAS, KRAS, AKT1, ERBB2; q<0.10) and seven putative tumor suppressor genes (ARID1A, TXNIP, CTNNB1, PIK3RI, CDKN2A, KLF5, STAG2; q<0.10) significantly regulated between tumor and control, which were formerly reported to be altered in BC." (PMID 30419021, 2018). "It should be noted that deletions of the CDKN2A/B and RB1 suppressor genes are present in T-ALL (70% and 12%, respectively) and B-ALL (36% and 8%, respectively) in which they contribute to the disruption of the tumor suppressor pathways in ALL." (PMID 29642462, 2018). "It was concluded that ANRIL's function may be, at least in part, to repress the CDKN2A and CDKN2B tumor suppressors." (PMID 30460243, 2018). "Antiangiogenic potential was also observed in testing the decitabine antimetabolite guadecitabine, that was shown to reactivate a few epigenetically silenced tumor suppressor genes: CDKN2A, DLEC1, RUNX3 and reduce tumor growth via inhibition of angiogenesis in a hepatocellular carcinoma model." (PMID 30103412, 2018).